DAPK2 (death associated protein kinase 2)
Description:
Calcium/calmodulin-dependent serine/threonine kinase involved in multiple cellular signaling pathways that trigger cell survival, apoptosis, and autophagy. Regulates both type I apoptotic and type II autophagic cell death signals, depending on the cellular setting. The former is caspase-dependent, while the latter is caspase-independent and is characterized by the accumulation of autophagic vesicles. Acts as a mediator of anoikis and a suppressor of beta-catenin-dependent anchorage-independent growth of malignant epithelial cells. May play a role in granulocytic maturation. Regulates granulocytic motility by controlling cell spreading and polarization. Isoform 2 is not regulated by calmodulin. It can phosphorylate MYL9. It can induce membrane blebbing and autophagic cell death.
Synonyms: DRP-1; MGC119312; DRP1
Tractability: Small molecule: a structure with a bound ligand is known; a high-quality ligand is known; it has a high-quality binding pocket; it belongs to a druggable protein family. PROTAC: ubiquitination databases record sites on it; a small molecule that binds it is known.
Target class: CAMK protein kinase group; Kinase; CAMK protein kinase DAPK family; Protein Kinase; Enzyme
Gene: Protein-coding gene on chromosome 15 (63,907,036 to 64,072,033, reverse strand). Ensembl gene ENSG00000035664.
Subcellular location: Cytoplasm; Cytoplasmic vesicle, autophagosome lumen
Subcellular location (Human Protein Atlas): Golgi apparatus; Vesicles
Pathways (Reactome):
Programmed Cell Death: Caspase activation via Dependence Receptors in the absence of ligand
Gene Ontology:
Molecular function: ATP binding; calmodulin binding; identical protein binding; protein binding; protein serine kinase activity; protein serine/threonine kinase activity; protein kinase activity
Biological process: anoikis; intracellular signal transduction; positive regulation of eosinophil chemotaxis; positive regulation of neutrophil chemotaxis; protein phosphorylation; regulation of intrinsic apoptotic signaling pathway; apoptotic process; positive regulation of apoptotic process; protein autophosphorylation; regulation of apoptotic process; regulation of autophagy; neutrophil migration
Cellular component: cytoplasm; nucleus; autophagosome lumen
Genetic constraint (gnomAD): Loss-of-function variants: 35 observed, 43.98 expected, observed/expected ratio (o/e) 0.8, 90% interval 0.61 to 1.05. The upper end of that interval is the gene's LOEUF score, 1.05, which puts it in group 4 of 6, group 1 being the genes least tolerant of losing a copy. Missense variants: 452 observed, 491.93 expected, observed/expected ratio (o/e) 0.92, 90% interval 0.85 to 0.99. Synonymous variants: 172 observed, 185.8 expected, observed/expected ratio (o/e) 0.93, 90% interval 0.82 to 1.05.
Homologues: Orthologues: mouse Dapk2 (97% identical), chimpanzee DAPK2 (84% identical), macaque DAPK2 (83% identical), dog DAPK2 (81% identical), rat Dapk2 (81% identical), pig DAPK2 (79% identical), guinea pig DAPK2 (79% identical), rabbit DAPK2 (79% identical), tropical clawed frog dapk2 (69% identical), zebrafish dapk2a (63% identical), zebrafish dapk2b (62% identical), macaque DAPK3 (61% identical). Paralogues in human: DAPK1 (62% identical), DAPK3 (62% identical), MYLK (36% identical), NEXN (15% identical).
Diseases named in the same sentence as DAPK2 in open-access papers:
DAPK2 is named in the same sentence as 47 diseases in open-access papers, as found by Europe PMC text mining. Sharing a sentence is not in itself a finding about the gene and the disease. The quoted sentences say what the papers report.
breast carcinoma (13 papers, 2016 to 2026). "Death‐associated protein kinase 2 (DAPK2) is a serine/threonine kinase linked to various forms of malignancy, such as breast cancer." (PMID 39971705, 2025). "DAPK2 is a serine/threonine kinase that has been linked to various malignancies, such as breast cancer." (PMID 39971705, 2025). "A recent study shows that miR-520 h promotes the drug resistance of human breast cancer cells through protecting cells from paclitaxel-induced apoptosis by targeting death-associated protein kinase 2 (DAPK2)." (PMID 34912799, 2021). "The expression of miR-520h promoted paclitaxel resistance of human breast cancer cells through suppressing death-associated protein kinase 2 (DAPK2) expression and protecting the cells from paclitaxel-induced apoptosis." (PMID 34589423, 2021). "MiR-520h is also crucial for DAPK2 (Death-associated protein kinase 2) regulation in breast cancer progression." (PMID 28182660, 2017). "Mir-520h induced suppression of DAPK2 is associated with a poorer prognosis and lymph node metastasis in breast cancer patients." (PMID 28182660, 2017). "This study aimed to study the LOC101928988 regulatory effect on the DAPK2 expression in breast cancer." (PMID 39971705, 2025). "This study includes a well‐defined objective centered on understanding the regulatory relationship between LOC101928988 and DAPK2 in breast cancer, which addresses a critical gap in the current cancer research landscape." (PMID 39971705, 2025). "As in this study, DAPK2 is also downregulated by miR-520h in breast cancer and miR-520g in epithelial ovarian cancer and it contributes to chemoresistance." (PMID 36900258, 2023). "miR-520 h directly inhibited DAPK2 expression, and DAPK2 suppression was important in miR-520 h-mediated paclitaxel resistance in breast cancer cells." (PMID 27049921, 2016). "miR-520 h, a member of the miR-520 family, reportedly downregulates tumor suppressor DAPK2 expression and contributes to chemoresistance in breast cancer." (PMID 27049921, 2016). "Moreover, miR‐520h can inhibit paclitaxel‐induced apoptosis in breast cancer by suppressing the expression of DAPK2 and caspases." (PMID 39971705, 2025). "Over-expression of DAPK2 could abolish breast cancer cell drug resistance induced by miR-520h, suggesting miR-520h-DAPK2 axis is a potential functional target for breast cancer therapy." (PMID 34422899, 2021). "Recently, Su showed that miR-520h could enhance the chemoresistance of breast cancer cells to paclitaxel by targeting DAPK2 and that miR-520h expression might be an indicator of poor prognosis in breast cancer patients." (PMID 32775453, 2020). "Hence, DAPK2 could be considered as a crucial gene that triggers cell death and suppresses cell proliferation in breast cancer cells." (PMID 39971705, 2025). "The objective of this study was to examine the expression profile of DAPK2 and its antisense lncRNA LOC101928988 within the mTORC signaling pathway in breast cancer, focusing specifically on their involvement in autophagy." (PMID 39971705, 2025). "Our results revealed that the expression of DAPK2 and LOC101928988 was downregulated in tumoral tissues compared to that in the control group, indicating their potential roles in breast cancer pathogenesis." (PMID 39971705, 2025). "The inhibition of FASN can induce apoptosis in breast cancer cells through upregulating pro-apoptotic genes BNIP3, DAPK2, and TRAIL." (PMID 29093680, 2017). "Overall, our results suggest that alterations in the levels of DAPK2 and LOC101928988 may be involved in tumor initiation and progression in breast cancer." (PMID 39971705, 2025). "Our findings revealed that dysregulation of DAPK2 and LOC101928988 might play a role in the initiation and progression of breast cancer." (PMID 39971705, 2025). "The results of our study revealed that changes in the expression of DAPK2 and LOC101928988 could be correlated with the initiation and progression of breast cancer." (PMID 39971705, 2025).
diabetic cardiomyopathy (10 papers, 2017 to 2025). Diabetic cardiomyopathy is a disorder of the heart muscle in people with diabetes. "For example, lncRNA transcripts of myocardial infarction (lncMIAT) can impact diabetic cardiomyopathy by constraining miR-22-3p for the up-regulation of Death-associated protein kinase 2 (DAPK2)." (PMID 34753394, 2022). "The same lncRNA has been associated with diabetic cardiomyopathy (DCM) for it affects the expression of death-associated protein kinase 2 (DAPK2) by sponging miR-22-3p: the resulting up-regulation of DAPK2 itself leads to cardiomyocyte apoptosis in DCM." (PMID 32605220, 2020). "It has been found that MIAT facilitated diabetic retinopathy via activating TGF-β1 signaling and induced cardiomyocyte apoptosis in diabetic cardiomyopathy by targeting the miR-22-3p/DAPK2 axis." (PMID 34553078, 2021). "For example, MIAT serves as a ceRNA to increase DAPK2 through sponging miR‐22‐3p in diabetic cardiomyopathy." (PMID 33009725, 2020). "In diabetic cardiomyopathy, high glucose induces the expression of myocardial infarction-associated transcript (MIAT) and upregulates the death-associated protein kinase 2 (DAPK2) expression by sponging miR-22-3p, which consequently leads to cardiomyocyte apoptosis." (PMID 35990951, 2022). "The lncRNA MIAT sponges miR-22-3p to upregulate DAPK2 in diabetic cardiomyopathy." (PMID 32796679, 2020). "Another study showed that lncRNA MIAT could function as an opposing endogenous RNA to increase DAPK2 levels by sponging miR‐22‐3p, ultimately resulting in the apoptosis of cardiomyocytes, a critical process involved in the development of diabetic cardiomyopathy." (PMID 39971705, 2025). "In a rat model of diabetic cardiomyopathy, MIAT and circMAP3K5 upregulate DAPK2 expression through competitive binding to miR-22-3p, which in turn promotes cardiomyocyte apoptosis." (PMID 40630623, 2025).
lung carcinoma (7 papers, 2015 to 2026). "RESULTS: Eight PANoptosis-related genes (DAPK2, CAV1, PDK4, IL3RA, NOTCH1, CHMP4B, IRAK1, and SFN) were identified as being significantly associated with lung cancer." (PMID 41760846, 2026). "The data were consistent with a significant impairment of mitochondrial integrity in response to DAPK2 depletion and, in the case of A549 lung cancer cells, activation of DAPK1." (PMID 25741596, 2015). "Furthermore, DAPK2 was also negatively correlated with miRNA-520g-3p and miRNA-520h in both histological subtypes of lung cancer (p < 0.01)." (PMID 36900258, 2023).
gastric cancer (5 papers, 2011 to 2020). A primary or metastatic malignant neoplasm involving the stomach. "It promotes oxaliplatin-resistant gastric cancer cell invasion and proliferation by decreasing E2F transcription factor 1 (E2F1) and death-associated protein kinase 2 (DAPK2) expression." (PMID 32944391, 2020). "Similarly, miR-135a has also been shown to potentiate oxaliplatin resistance of gastric cancer cells by down-regulating expression of E2F transcription factor 1 (E2F1) and death-associated protein kinase 2 (DAPK2)." (PMID 32192494, 2020).
colorectal cancer (4 papers, 2020 to 2025). A primary or metastatic malignant neoplasm that affects the colon or rectum. "Similarly, in colorectal cancer, reduced DAPK2 expression has been associated with tumor advancement and the spread of cancer cells." (PMID 39971705, 2025). "In colorectal cancer, miR-1285-3p improved colorectal cancer cell proliferation and escape from apoptosis by targeting DAPK2." (PMID 34422899, 2021). "Here, we demonstrate that DAPK2 expression in colorectal cancer is controlled by miR-1285, thus providing further insight into the post-transcriptional layer of DAPK2 regulation." (PMID 32244500, 2020). "Similarly, another study reported that DAPK2 upregulation induces cell arrest and apoptosis in colorectal cancer." (PMID 39971705, 2025). "In addition, altered DAPK2 gene expression serves as a potential biomarker for the diagnosis of a variety of diseases such as Parkinson’s disease, colorectal cancer, and gliomas." (PMID 40630623, 2025). "miR‐1285, an oncogenic miRNA, targets DAPK2 mRNA and inhibits its expression in colorectal cancer." (PMID 39971705, 2025). "Finally, we propose a role for DAPK2 as a mediator of cell cycle arrest and apoptosis in colorectal cancer cells treated with an anti-miR-1285 inhibitor." (PMID 32244500, 2020).
bladder cancer (3 papers, 2023 to 2025). "A significant decrease in DAPK2 levels has been reported in bladder cancer cells because miR‐106 efficiently binds to the 3′‐UTR of DAPK2." (PMID 39971705, 2025).
Obesity (3 papers, 2016 to 2021). Accumulation of substantial excess body fat. "In human obesity, DAPK2 knockdown led to decreased adipocyte autophagic clearance." (PMID 27049921, 2016). "DAPK2 is expressed mainly in mature adipocytes rather than stromal vascular cells in WAT, and DAPK2 mRNA levels are strongly downregulated according to obesity status in human and mice and gradually recover after bariatric surgery-induced weight loss." (PMID 31357643, 2019).
thyroid cancer (3 papers, 2018 to 2025). "The research has shown that DAPK2 is a critical factor in various malignancies, including lung, colorectal, and thyroid cancer." (PMID 39971705, 2025). "The aberrant methylation, and hence silencing, of DAPK2 has been reported to play a critical role in thyroid cancer tumorigenesis and progression." (PMID 30473937, 2018). "Moreover, DAPK2 plays a crucial role in the initiation and progression of thyroid cancer, as it contributes to tumor development and the ability to resist TRAIL‐induced apoptosis through autophagic degradation of I‐κBα." (PMID 39971705, 2025). "In conclusion, we developed a novel seven-mRNA (CDKN2A, FGF7, CTSB, HAP1, DAPK2, DNAJB1, ITPR1) risk model and nomogram that could help assess the prognosis of patients and guide clinical decision-making and individualized therapy for differentiated thyroid cancer." (PMID 35459137, 2022).
diabetic retinopathy (2 papers, 2021 to 2025). "Additionally, a disease–gene association circos plot generated using RAW Graphs 2.0 showed tight linkage of hub DEGs such as DAPK2, DUSP3, IL6R, and UGP2 to cardiovascular comorbidities, including heart failure, diabetic retinopathy, cardiomyopathy, and pulmonary hypertension." (PMID 41262879, 2025).
Hodgkins lymphoma (2 papers, 2017 to 2019). A heterogeneous group of malignant lymphoid neoplasms of B-cell origin characterized histologically by the presence of Hodgkin and Reed-Sternberg (HRS) cells in the vast majority of cases. "The authors showed that a single injection of DAPk2Δ73-CD30L prevented tumor development in mice xenografts, while raising awareness for the need to thoroughly assess DAPk2 expression in primary Hodgkin lymphomas." (PMID 30783518, 2019). "This ability of Decitabine to also reactivate DAPk2 expression in Hodgkin lymphoma cell lines has also been demonstrated." (PMID 28976934, 2017). "The first proof of concept studies have shown that a targeted delivery of a constitutively active DAPK2 to CD30-positive Hodgkin’s lymphoma cells selectively kills CD30-positive and DAPK2-negative but not CD30-positive and DAPK2-positive HL cells." (PMID 28976934, 2017). "Similarly, a proof-of-concept study demonstrated that Decitabine also restored down-regulated DAPk2 tumor suppressor activity in Hodgkin's lymphoma cells." (PMID 30783518, 2019). "Using this approach, the first DAPk2-based fusion protein, a human DAPk2Δ73 genetically fused to the extracellular domain of human CD30L, was developed for the treatment of Hodgkin's lymphoma." (PMID 30783518, 2019).
laryngeal carcinoma (2 papers, 2021). Carcinoma that arises from the laryngeal epithelium. "Our data confirmed that RCN1, DNAJA2, LASP1 and IBSP were up-regulated while LAT2, FUZ, HOOK2 and DAPK2 were down-regulated in laryngeal cancer." (PMID 34976784, 2021). "This suggests that EGFR and INHBA can serve as prognostic hub genes for laryngeal cancer collectively with pRS genes (CFLAR, DAPK2, TSC2, CAPN10, MBTPS2, PEX14, FADD and ST13)." (PMID 34093817, 2021).
lung adenocarcinoma (2 papers, 2019 to 2023). A carcinoma that arises from the lung and is characterized by the presence of malignant glandular epithelial cells. "The CDKN1A and DAPK2 genes are notable for being negatively correlated with and targeted by multiple miRNAs from these clusters in the two most common subtypes of NSCLC (lung adenocarcinoma and SCC)." (PMID 36900258, 2023). "Additionally, recent study revealed that DAPK2, MFSD2A, THSD1 and WNT7A were oncogenes which showed high expression and low methylation in lung adenocarcinoma." (PMID 30899432, 2019).
melanoma (2 papers, 2021 to 2023). A malignant, usually aggressive tumor composed of atypical, neoplastic melanocytes. "We obtained the risk scores of patients with melanoma: risk score = (−0.379123977 × expression of IFNG) + (−0.662084468 × expression of DAPK2) + (0.342818269 × expression of ATG9B) + (0.406559238 × expression of PTK6) + (0.807218069 × expression of BIRC5) + (0.364523721 × expression of EGFR)." (PMID 36690663, 2023). "The results confirmed that APOL1 have higher expression in GSE46517 while ATG16L2, DAPK2, ATG9B and EGFR have lower expression in GSE15605 for primary melanoma compared with normal skin." (PMID 34809598, 2021). "Melanoma patients with high expression of IFNG and DAPK2 have a better prognosis." (PMID 36690663, 2023).
thyroid tumor (2 papers, 2022 to 2023). A benign or malignant neoplasm affecting the thyroid gland. "The effect of DAPK2 on differentiated thyroid tumours has remained to be reported." (PMID 35459137, 2022).
amyloidosis (1 paper, 2021). A disorder characterized by the localized or diffuse accumulation of amyloid protein in various anatomic sites. "Although the role of DAPK2 in amyloidosis in unknown, another family member, DAPK1, promotes the phosphorylation and amyloidogenic processing of APP." (PMID 30361487, 2021).
B cell lymphoma (1 paper, 2017). "Tumor suppressor activities have been shown for DAPk1 and DAPk2 and they are downregulated in e.g., Hodgkin’s (HL) and B cell lymphoma (CLL), respectively." (PMID 28976934, 2017). "The promoter region of DAPk1 and DAPk2 (members of the DAPk gene family) are reportedly hypermethylated in multiple tumor types with the highest frequency of DAPk methylation detected in B-cell lymphoma." (PMID 28976934, 2017).
bladder tumor (1 paper, 2025). "Consequently, miR‐106 suppresses DAPK2 transcription and inhibits apoptosis in bladder tumor cells." (PMID 39971705, 2025).
colon cancer (1 paper, 2024). "Consistently, they revealed that high DAPK2 levels can facilitate apoptosis in colon cancer cells." (PMID 38779664, 2024).
endothelial dysfunction (1 paper, 2025). In vascular diseases, endothelial dysfunction is a systemic pathological state of the endothelium (the inner lining of blood vessels) and can be broadly defined as an imbalance between vasodilating and vasoconstricting substances produced by (or acting on) the endothelium. "Through its interaction with DAPK2, MIABEPIR inhibits autophagy and disrupts tight junction integrity, leading to increased BBB permeability and endothelial dysfunction." (PMID 40000424, 2025).
hepatocellular carcinoma (1 paper, 2021). A malignant tumor that arises from hepatocytes. "The low expression of DAPK2 in hepatocellular carcinoma (HCC) attenuates the protective effect of DNA damage mediated by autophagy." (PMID 33777735, 2021).
hyperandrogenism (1 paper, 2022). Excessive secretion of androgens from the adrenal glands or gonads. "DAPK2 was identified and validated as a critical biomarker associated with the immune disorder and granulosa cell dysfunction in PCOS with hyperandrogenism, acting as an independent predictor of embryo implantation failure." (PMID 36060967, 2022).